CRP (C-reactive protein)
Diseases named in the same sentence as CRP in open-access papers (continued):
Sharing a sentence is not in itself a finding about the gene and the disease.
infection (continued). "However, DPP-4i users were more frequently under renin-angiotensin-aldosterone system blockers and, upon admission, appeared to have a slightly more severe form of infection, with higher plasma glucose and C-reactive protein (CRP) concentrations." (PMID 36289885, 2022). "The effects of inflammation and/or infection on iron markers synthesis are well-known, but this effect would not explain the associations of sTfR found since adjustment for CRP levels did not attenuate them." (PMID 36670881, 2022). "Furthermore, the degree of differential expression found for these proteins was equivalent to that of the well-known infection biomarker, C-reactive protein (CRP), which is widely utilized in clinical settings as a diagnostic marker of inflammation." (PMID 35668098, 2022). "However, the changes of GLB and CRP concentration is slight during 5 years, and all above hits, which immunoregulation has undergone hidden changes after primary infection to maintain the immune homeostasis." (PMID 35794923, 2022). "In the presence of an acute-phase inflammation or infection, CRP levels are increased dramatically." (PMID 35359771, 2022). "CRP typically increases within hours of the onset of infection and / or inflammation." (PMID 35178206, 2022). "The utility of the kinetic properties of CRP was shown to improve the diagnostic ability of postsurgical infections from non-infectious inflammation." (PMID 35897672, 2022). "In addition, the biomarkers PCT, WBC count and CRP, which indicate the severity, prognosis and outcomes of infections, are of great use in clinical treatment." (PMID 36329535, 2022). "CRP, an important opsonin of systemic inflammation and infection severity, could enhance phagocytosis and promote clearance by binding to phosphocholine in the membranes of host cells and pathogens." (PMID 36033814, 2022). "Oxygen saturation, hemoglobin levels, infection-related indicators, lymphocyte and platelet counts, C-reactive protein, serum albumin, liver and kidney function, and lactate dehydrogenase in improvement group were statistically significant between the improvement and death groups." (PMID 33762058, 2022). "CRP’s main role in inflammation is the activation of the C1q molecule in the complement pathway, leading to the opsonization of pathogens, hence actively participating in the immune response to infection." (PMID 35897672, 2022). "This study was conducted to determine the diagnostic accuracy of C-reactive protein to rule out surgical site infection in patients undergoing hip fracture surgery." (PMID 35991254, 2022). "When grouping infected patients by infection subgroups, patients in the definitive infection group demonstrated significantly higher median serum CRP levels (24.3 mg/l), when compared to probable, possible infection groups and PJI unlikely group (8 mg/l, 8.3 mg/l, 3.6 mg/l, respectively, p < 0.05)." (PMID 33515325, 2022). "CRP is an acute phase reaction protein that is released primarily from hepatocytes in response to increased concentrations of interleukin (IL)-6 and is elevated during tissue damage, infection, and inflammation." (PMID 35060938, 2022). "Deviations from the normal rise in CRP may indicate an infection and diagnose surgical complications at an early stage." (PMID 35350520, 2022). "Nevertheless, our findings support current knowledge on serious infections and underline that increased systolic blood pressure and decreased heart rate, total NEWS score, and CRP during hospitalization may indicate infection control." (PMID 35406374, 2022). "In agreement with this previous study, results from the present study found abnormal levels of aspartate aminotransferase, lactate dehydrogenase, C-reactive protein, white blood cell count, neutrophil counts, and lymphocyte counts late in the course of infection." (PMID 35546539, 2022).
infection (continued). "Because CRP reflects the acute phase systemic inflammatory response, a rise in the serum CRP concentration can be considered a sensitive measure of the presence of infection." (PMID 36083881, 2022). "CRP and ESR are associated with infection and tissue injury." (PMID 36703984, 2022). "C-reactive protein (CRP) is a normal plasma protein and elevates during cytokine-mediated response to most forms of tissue injury, infection and inflammation and serum CRP values are widely measured in clinical practice as an objective index of disease activity." (PMID 35794133, 2022). "CRP levels begin to rise between 10 and 12 h after onset of infection, and peak at 48 h." (PMID 35345614, 2022). "The initial (OR, 1.627; 95% CI, 1.342–1.973) and mid‐term (OR, 1.599; 95% CI, 1.349–1.895) blood glucose levels were related to markers of infection, such as C‐reactive protein (CRP) (OR, 1.010; 95% CI, 0.995–1.026) and the ESR (OR, 1.045; 95% CI, 1.026–1.064)." (PMID 34967028, 2022). "The slow replication of E. canis might be the cause of the delayed injury or inflammation found between 3 and 4 weeks after infection, and CRP concentrations may therefore increase in both acute and chronic CME." (PMID 34840450, 2021). "However, determining CRP levels has proven to have some limitations, especially when detecting an early infection in newborns." (PMID 34307663, 2021). "When a model combining PSP and CRP was used, the ROC AUC improved to 0.90 (0.87–0.92) with higher sensitivity 0.81 (0.77–0.85) and specificity 0.84 (0.79–0.90) for discriminating infection from non-infection." (PMID 34049579, 2021). "In the blood of healthy people, the level of C-reactive protein is usually very low, and its concentration in the blood can increase markedly and rapidly when there is an acute inflammatory reaction induced by trauma and infection." (PMID 34900028, 2021). "Therefore, although upon infection (soluble), CRP levels are elevated almost everywhere in the body, CRP will only activate macrophages in tissues where CRP is bound to its ligands, such as particular strains of bacteria." (PMID 34769069, 2021). "C-reactive protein (CRP) is an established biomarker for the assessment of inflammation and its severity in patients who present to medical facilities and can be used as a reliable, fast and inexpensive indicator of the infection type." (PMID 34863104, 2021). "CRP levels can be elevated in patients with acute inflammation or infection." (PMID 34620099, 2021). "While higher-than-normal ESR and CRP levels are diagnostic criteria for infection and failure of the treatment, the levels do not seem to be related to prognosis." (PMID 34722006, 2021). "Persistently elevated serum CRP levels after resection arthroplasty may predict recurrent infections." (PMID 34768700, 2021). "Since CRP serum levels are particularly elevated during bacterial infections, CRP-induced IL-23 production may provide a rapid mechanism to shape systemic anti-bacterial/fungal immunity upon infection." (PMID 34769069, 2021). "Therefore, the deposition of CRP at the site of infection can be detected, especially in the liquid phase." (PMID 34372816, 2021). "Although CRP increased in patients of the D + T- group who developed a secondary infection compared to those who did not (p = 0.003), this rise was only apparent from day 2 post-infection onwards." (PMID 34781995, 2021). "There is growing evidence that CRP plays important roles in inflammatory processes and host responses to infection including the complement pathway, apoptosis, phagocytosis, nitric oxide (NO) release, and the production of cytokines, particularly interleukin-6 and tumor necrosis factor-α." (PMID 33534859, 2021). "In Huh7 cells, increased expression of acute-phase proteins, such as C-reactive protein and serum amyloid A1, was observed with the progression of infection, whereas FFAR2 and STEAP4 with metalloreductase activity showed significantly higher upregulation than other genes." (PMID 34899651, 2021).
infection (continued). "The elevated levels of CRP might be due to that CRP only was measured when clinically indicated, most often to monitor the course of an infection." (PMID 34332571, 2021). "A rise of IL-6 levels during TCZ therapy may flag masked infections in patients with suppressed CRP levels." (PMID 33804790, 2021). "In this study we have reported CRP trends that can provide a timely indication of infection status." (PMID 34856956, 2021). "Similarly, our study was able to demonstrate that a postoperative infection after treatment of an acetabular fracture can be detected by the maximum CRP and a second peak with a sensitivity of 83% and a specificity of 81%." (PMID 34768504, 2021). "Of particular interest are the effects of genetic variants on CRP concentrations during its acute phase response to infections, trauma, and surgery because these may exceed basal CRP levels by over 100-fold." (PMID 33628645, 2021). "Moreover, the infection indicators of white blood cell, procalcitonin, and CRP were all significantly reduced." (PMID 34656132, 2021). "Besides the prognostic value of CRP after trauma, increased CRP levels in febrile children in the emergency department should also initiate further infection diagnostics such as blood culture and smear tests." (PMID 33816396, 2021). "In addition, the target microbiome affected the level of CRP in blood and the proportion of granulocytes (monocytes) in CSF, which further influenced the degree of infection and inflammation." (PMID 34100633, 2021). "Indeed, CRP in our study proved to be very ineffective in discriminating infection from inflammation." (PMID 34645893, 2021). "Furthermore, blood test results also showed infection indexes such as CRP and the blood leukocyte level as significantly lower in the ICS group than in the control group, suggesting that ICS can effectively reduce the risk of postoperative infection." (PMID 33815566, 2021). "CRP is usually activated at the time of inflammation and infection." (PMID 34828008, 2021). "C reactive protein (CRP) is an acute phase reactant that is elevated in infections." (PMID 34446820, 2021). "Baseline serum concentrations of CRP are less than 3 mg/L, but this level may increase to 500 mg/L within 24–48 h from the onset of infection or inflammation." (PMID 34769069, 2021). "In AL group, bacteriological concentration in drainage fluid could diagnose AL before infection indexes such as CRP, WBC, and PCT." (PMID 34848817, 2021). "The primary aim of this study is to conduct a US economic evaluation of FebriDx, a novel, rapid point-of-care test that simultaneously measures two key infection biomarkers, C-reactive protein and Myxovirus resistance protein A (MxA) to accurately differentiate viral from bacterial infection." (PMID 34703832, 2021). "Furthermore, a single patient showed extreme values for CRP due to an infection and was excluded for analysis." (PMID 34832948, 2021). "C-reactive protein (CRP) is a commonly used biomarker for infection worldwide." (PMID 34828783, 2021). "Besides these factors, treatment and infection indicators, including blood count, CRP, and PCT, were also analyzed." (PMID 33506027, 2021). "Identification of increase CRP as a poor prognostic marker in SAP provides an intriguing possibility that the attempt to reduce inflammation and possible associated infection may reduce the excess mortality and morbidity burden of SAP." (PMID 31037709, 2021). "Since the patients included in the study were in the early stages of infection, presenting within four days of symptoms, low CRP could indicate a weak baseline immune response, thereby resulting in a worse clinical outcome." (PMID 33680618, 2021). "The levels of CRP are elevated after infection and inflammation." (PMID 34281552, 2021). "Tests on June 2 and June 28 showed increases in both PCT and CRP, indicating infection." (PMID 33791233, 2021).
infection (continued). "Few participants in our study had detectable serum CRP concentrations > 10 mg/L, indicating that our study sample may not include participants presenting with acute inflammation or infection." (PMID 33807159, 2021). "This could be accomplished in a randomized controlled trial (RCT) of vaccination versus placebo with wearable tracking of HRV in comparison to CRP levels, antibody titers, and protection against infection." (PMID 34236995, 2021). "The median CRP value (in 6 of 8 infection episodes) was 88.9 mg/L (range: 11–272 mg/L)." (PMID 34832555, 2021). "C-reactive protein as a proxy for infection correlated negatively with blood eosinophil counts." (PMID 34179040, 2021). "Patients with factors that may affect CRP levels (inflammatory arthritis, concomitant infections, liver and kidney diseases, and intensive care admissions) were excluded." (PMID 34856956, 2021). "CRP trend uses all the changes in CRP concentration, including CRP decrements, which can also help in the process of differentiation between both types of infection." (PMID 34863104, 2021). "The inclusion of post-trauma and post-operative populations with a very low baseline risk of infection might have limited the ability of CRP and PCT to diagnose infection." (PMID 34049579, 2021). "Furthermore, changes in PCT and CRP kinetics upon occurrence of a secondary infection and accuracy of these biomarkers for the detection of a secondary infection were assessed." (PMID 34781995, 2021). "The increase in CRP serum concentration is comparatively slow during the first 24-48 h of infection, which may reduce the test’s sensitivity." (PMID 34912626, 2021). "In all patients, infection by SARS-CoV-2 was diagnosed through a CRP-test." (PMID 34045976, 2021). "PCT has also been shown to have early detection post-infection compared to CRP." (PMID 34522543, 2021). "Specifically, elevated CRP level is independently associated with increased incidence of 30-day CSI, and the association was consistent across different stratified analyses according to infection, organ failure, MELD score, and liver tumor." (PMID 34439862, 2021). "The authors found that a history of second-trimester pregnancy loss, nulliparity, a cervix dilated more than 4 cm, membranes bulging into the vagina, and infection (i.e., white blood cells (WBC) ≥ 13,600/ mm3 or C-reactive protein (CRP) > 15 mg/L) are associated with emergency suture failure." (PMID 33803886, 2021). "Participants with infections and CRP levels > 100 mg/L were recruited from the medical wards of a teaching hospital and assisted to complete a demographic and vascular risk factor questionnaire, and to undergo non-mydriatic retinal photography (Canon CR5-45NM, Japan)." (PMID 34446820, 2021). "Both CRP and CRP/PCT could therefore be helpful in guiding decisions in a two-stage decision-making process: a PCT value above 0.5 points to potential infection." (PMID 33777975, 2021). "CRP involves an acute inflammation protein, the level of which can increase due to an infection." (PMID 35011910, 2021). "Serum CRP levels are highly elevated in these acute planktonic infections." (PMID 34572314, 2021). "Considering that CRP is associated with surgery and infection, the negative predictive value of combined cTnI and CRP biomarkers is higher than either value alone." (PMID 34859069, 2021). "In conclusion, PCT and CRP/PCT values upon admission could assist in diagnosing infection in patients with solid tumors and should be considered in the decision-making process regarding their clinical management." (PMID 33777975, 2021). "CRP production is stimulated by IL-6 and is produced by the liver as a response to infection." (PMID 34590796, 2021). "Plasma CRP concentrations increase in the liver after surgical trauma and infection." (PMID 33485312, 2021). "As a single parameter, maximum CRP predicts an early infection with 75% sensitivity." (PMID 34768504, 2021).
infection (continued). "In addition, we assess the post-traumatic infections by biomarkers of post-traumatic inflammation IL-6, IL-10, CRP, and WBC." (PMID 34568354, 2021). "CRP has been widely used to evaluate the severity of inflammation and infection." (PMID 34726101, 2021). "Of these, three continued with reimplantation within 1 week of occurrence, because the surgeons deemed them “infection-free”, while the other nine were treated conservatively and exhibited reduced serum CRP levels at the two-week follow-up (median decline in CRP: 64.4%; IQR: 38.1–90.6%)." (PMID 34856956, 2021). "C-reactive protein (CRP), which is widely used to monitor inflammatory conditions or infection, as well as a low preoperative hemoglobin level and lymphocyte count, may be indicators of mortality." (PMID 34765379, 2021). "The relative increase in the CRP value in the fatal group may have reflected cytokine storm and the complications of secondary infection, but the exact mechanism remains unknown." (PMID 33925061, 2021). "Elevated CRP (in the absence of any identifiable acute cause, such as infection, illness, physical trauma, etc.)is indicative of underlying systemic inflammation and higher CVD risk." (PMID 34444779, 2021). "As such, we can hypothesize that the quantification of interleukins and CRP from the blood serum may have revealed an ongoing infection, and, thereby, this provides more soundness to the interpretation of the obtained data." (PMID 35011159, 2021). "CRP levels are acutely elevated during infection or inflammation." (PMID 34407875, 2021). "CRP is a glycosylated protein, an acute-phase reactant, that is synthesized by liver hepatocytes stimulated by IL-6 and IL-8 in response to tissue damage or infection." (PMID 34200950, 2021). "This may account for the superior performance of CRP compared to PCT which is generally thought to show a slower response to infection than PCT." (PMID 33544738, 2021). "We could show that levels of IL-6 and CRP are significantly higher in trauma patients who develop post-traumatic infection." (PMID 34568354, 2021). "It has been documented that C-reactive protein (CRP) is commonly used as a marker of acute inflammatory syndrome, and its plasma concentration has always been related to the clinical course of the infection, with decreasing levels suggesting resolution of the infection." (PMID 34645893, 2021). "Interestingly, the overall maximal CRP (pre- and postoperatively) appeared to be higher in the infection group (Mann–Whitney, p = 0.049)." (PMID 34768504, 2021). "The pentraxin, CRP is one of several acute phase reactants that are produced by hepatic tissues after specific receptor activation by a range of stimuli including the cytokines IL-1 and IL-6 in response to injury, infection or inflammation." (PMID 33853634, 2021). "CRP did not significantly mediate the association of ATS with all-cause or infection-related mortality." (PMID 34315941, 2021). "Based on the kinetics of CRP, it is not preferred as an early prognostic and diagnostic marker; however, it has been shown that serial measurements of CRP could reliably rule-out infection 24 h after suspicion." (PMID 33407770, 2021). "Furthermore, in addition to proof of concept, IPIs’ correlation with C-reactive protein (CRP) levels as a clinical infection marker was evaluated." (PMID 35011910, 2021). "However, applying the maximum CRP value for detection of an infection yielded a maximum sensitivity of 75% and a specificity of 56.86%, respectively (AUC: 0.7028)." (PMID 34768504, 2021). "miR-21 expression was shown to be induced by inflammatory stimuli and its expression is correlated with C-reactive protein and fibrinogen levels, which indicates that EV miR-21 is worth to be further investigated as potential biomarker for infection/inflammation." (PMID 33468257, 2021).